ZNF883 (zinc finger protein 883)
Description:
May be involved in transcriptional regulation.
Tractability: PROTAC: ubiquitination databases record sites on it.
Gene: Protein-coding gene on chromosome 9 (112,988,129 to 113,012,242, reverse strand). Ensembl gene ENSG00000228623.
Subcellular location: Nucleus
Gene Ontology:
Molecular function: protein binding; DNA-binding transcription factor activity, RNA polymerase II-specific; RNA polymerase II cis-regulatory region sequence-specific DNA binding
Biological process: regulation of transcription by RNA polymerase II
Cellular component: nucleus; cytoplasm
Homologues: Orthologues: macaque ZNF883 (96% identical), pig ZNF883 (71% identical). Paralogues in human: ZNF658 (56% identical), ZNF528 (55% identical), ZNF30 (54% identical), ZNF546 (54% identical), ZNF568 (54% identical), ZNF571 (54% identical), ZNF189 (53% identical), ZNF33B (53% identical), ZNF16 (52% identical), ZNF226 (52% identical), ZNF573 (52% identical), ZNF585B (52% identical), and 164 more.
Diseases named in the same sentence as ZNF883 in open-access papers:
ZNF883 is named in the same sentence as 4 diseases in open-access papers, as found by Europe PMC text mining. Sharing a sentence is not in itself a finding about the gene and the disease. The quoted sentences say what the papers report.
glioblastoma (1 paper, 2023). The most malignant astrocytic tumor (WHO grade IV). "To investigate whether these genes with H4K5acK8ac-preferred promoters regulate glioblastoma stem-like properties, i. e., marker gene expression for stem cells and sphere formation efficiency, we disrupted ZNF883, RFX4, KLF11, and ZNF835 by siRNA knockdown in 0316-GSC cells." (PMID 37759202, 2023). "We identified a group of TF candidate genes with H4K5acK8ac-preferred promoters (e.g., ZNF883 and RFX4) and showed that they were also involved in the maintenance of glioblastoma stem-like properties." (PMID 37759202, 2023).
schizophrenia (1 paper, 2023). A major psychotic disorder characterized by abnormalities in the perception or expression of reality. "Among these, two lncRNAs, ZNF883 and HCP5, may play a role in the pathogenesis of schizophrenia." (PMID 37383091, 2023).
Sotos syndrome (1 paper, 2022). Sotos syndrome is a rare multisystemic genetic disorder characterized by a typical facial appearance, overgrowth of the body in early life with macrocephaly, and mild to severe intellectual disability. "In conclusion, we propose that NSD1 may participate in Sotos syndrome’s mechanism of action by regulating the function of lncRNA, inducing the down-expression of GSC, NDRG2 and SORBS1 and the up-expression of SFN and ZNF883." (PMID 35888078, 2022).
ZNF883 also shares sentences with these, for which no sentence is quoted: epilepsy (1 paper).